SCAP (SREBF chaperone)
Diseases named in the same sentence as SCAP in open-access papers (continued):
Sharing a sentence is not in itself a finding about the gene and the disease.
nonalcoholic steatohepatitis (2 papers, 2021 to 2022). "The SCAP/SREBP/INSIG1 trio promotes hepatic lipid remodeling to protect the liver from lipotoxic insults associated with the progression of nonalcoholic steatohepatitis progression." (PMID 34987591, 2021).
pancreas cancer (2 papers, 2024 to 2026). "Therefore, given these data, we conclude that SCAP is an essential gene in multiple types of cancers and is likely to be required broadly for growth in pancreatic cancer cell lines." (PMID 39240063, 2024). "Considering that the SREBP pathway is required for PDAC xenograft tumor growth, disease progression in KPC mice, and human pancreatic cancer cell lines are highly dependent on SCAP function, we next tested whether our observations are applicable to patients with PDAC." (PMID 39240063, 2024). "Here, we examined the requirement for the SREBP pathway and specifically its essential regulator SCAP for (i) PDAC initiation and disease progression in a genetically engineered mouse model (GEMM) of pancreatic cancer, (ii) growth of PDAC tumor xenografts, and (iii) growth of PDAC cells in culture." (PMID 39240063, 2024).
pneumonia (2 papers, 2021 to 2023). An acute, acute and chronic, or chronic inflammation focally or diffusely affecting the lung parenchyma, caused by an infection in one or both of the lungs (by bacteria, viruses, fungi, or mycoplasma.). "They reported that inhibition of C5a, which is considerably elevated in sCAP, protects against lung and liver injury in mice with pneumonia." (PMID 34356880, 2021). "In our study, IL-6 showed a trend of gradual upregulation with pneumonia severity, it was a selected feature for discrimination between uCAP and sCAP and correlated with the plasma levels of IL-8, which has been described to be significantly higher in sCAP patients compared to milder CAP." (PMID 37342494, 2023).
prostate carcinoma (2 papers, 2023). A carcinoma that arises from epithelial cells of the prostate gland. "Fatostatin, a specific inhibitor binds the SREBP-cleavage activating protein (SCAP) to block cholesterol biosynthesis, is able to inhibit tumor growth in vivo in a mouse prostate cancer experiment." (PMID 37089950, 2023).
Sepsis (2 papers, 2023 to 2025). Sepsis is defined as life-threatening organ dysfunction caused by a dysregulated host response to infection. "Survival analyses revealed that sepsis cases with low levels of mRNA of ADRB2, QDPR, SCAP, and TLR4 had worse overall survival." (PMID 38011291, 2023).
autoimmune disease (1 paper, 2022). A disorder resulting from loss of function or tissue destruction of an organ or multiple organs, arising from humoral or cellular immune responses of the individual to their own tissue constituents. "More happily, they found that SCAP knockout mice did not develop autoimmune diseases, and the PROPORTION of CD4+/CD8+ T cells in other tissues remained regular, which seems to indicate that SCAP knockout does not affect T cells in other normal tissues, which is a specific target." (PMID 36387147, 2022).
blood pressure (1 paper, 2017). "Association of SCAP polymorphisms with high blood pressure phenotype in Chinese children." (PMID 28542467, 2017).
cognitive decline (1 paper, 2025). "Reduction of SCAP suppresses cholesterol synthesis in the brain, leading to impaired synaptic transmission, disrupted long-term potentiation (LTP), and altered cognitive function, which contributes to the increased cognitive decline observed in diabetic states." (PMID 40649837, 2025).
coronary thrombosis (1 paper, 2008). Coagulation of blood in any of the coronary vessels. "The combination of the SREBF-2 C allele and the SCAP G allele was present in 8 of the 20 men (40%) with coronary thrombosis, whereas the SREBF-2 C allele in combination with the SCAP AA genotype was present in 2 of the 20 men (10%) with coronary thrombosis." (PMID 19116028, 2008).
endothelial dysfunction (1 paper, 2021). In vascular diseases, endothelial dysfunction is a systemic pathological state of the endothelium (the inner lining of blood vessels) and can be broadly defined as an imbalance between vasodilating and vasoconstricting substances produced by (or acting on) the endothelium. "This work revealed, for the first time, the molecular mechanisms by which sterol-resistant SCAP interacts with the inflammasome pathway, promoting endothelial dysfunction and atherosclerotic lesion development." (PMID 34094640, 2021). "Moreover, we observed that sterol-resistant SCAP significantly increased local inflammation and induced endothelial dysfunction in the aortas of SCAPD443N mice and SCAPD443N/ApoE-/- mice." (PMID 34094640, 2021). "Overall, we determined that, in addition to what has been observed for endothelial cells and macrophages, SCAP also regulates the activation of the NLRP3 inflammasome in VSMCs, thus inducing endothelial dysfunction and enhanced atherosclerotic progression." (PMID 34094640, 2021).
enteropathy (1 paper, 2016). "Indeed, conditional knockout of SCAP in Swann cells causes hypomyelination and conditional knockout of SCAP in the intestinal mucosa causes severe enteropathy." (PMID 27707816, 2016).
glioma (1 paper, 2021). A benign or malignant brain and spinal cord tumor that arises from glial cells (astrocytes, oligodendrocytes, ependymal cells). "Recently, miRNA-29 family (miR-29a/b/c) was proven as proliferation, invasion and migration suppressors for gliomas by targeting cell division cycle 42 (CDC42) and Sterol regulatory element binding protein 1 (SREBP-1)/SREBP cleavage-activating protein (SCAP) in animal models." (PMID 34066132, 2021).
Listeria monocytogenes infections (1 paper, 2016). "HSV-1 and Listeria monocytogenes infections marginally induced the expression of SCAP." (PMID 26900919, 2016).
lung adenocarcinoma (1 paper, 2022). A carcinoma that arises from the lung and is characterized by the presence of malignant glandular epithelial cells. "SREBP-1 and SCAP expression are strongly associated with disease progression and a poor prognosis in NSCLC, making them reliable biomarkers and potential molecular targets for the treatment of lung adenocarcinoma." (PMID 35806291, 2022).
lung diseases (1 paper, 2021). "Experimental studies are beginning to point to the role of the SCAP/SREBP pathway in the development of lung diseases in animals." (PMID 34249075, 2021).
Myocardial fibrosis (1 paper, 2023). "Despite of the small sample size, the lack of any identification of myocardial fibrosis with cardiac MRI suggests that myocardial scarring does not warrant further investigation in patients with sCAP." (PMID 38136744, 2023).
neuroblastoma (1 paper, 2021). Neuroblastoma (NB) is the most common solid, extracranial childhood tumor. "It is still unknown that whether the expression of the six genes, AR, SCAP, SREBF1, SREBF2, HMGCR, and CYP17A1 are closely associated with neuroblastoma patient survival." (PMID 34041015, 2021).
neuropathy (1 paper, 2016). A disorder affecting the nervous system that manifests with pain, tingling, numbness, and/or muscle weakness. "Disruption of the SCAP gene in astrocytes results inmicrocephaly, motor deficits and behavioral dysfunctions, which could bepartially rescued by the uptake of dietary lipids.Schwann cell SCAP mutant mice exhibit congenitalhypomyelination and neuropathy-related behavior, tremor, and abnormal gait." (PMID 27099785, 2016).
osteosarcoma (1 paper, 2020). A usually aggressive malignant bone-forming mesenchymal neoplasm, predominantly affecting adolescents and young adults. "In vitro biocompatibility was also examined in the behavior of osteosarcoma (Saos-2) cells, indicating that the sCaP bioceramics had no cytotoxicity effect." (PMID 33138182, 2020).
pancreatic ductal adenocarcinoma (1 paper, 2024). An infiltrating adenocarcinoma that arises from the epithelial cells of the pancreas. "However, the role of the SREBP pathway and its central regulator SREBP cleavage activating protein (SCAP) in pancreatic ductal adenocarcinoma (PDAC) has not been studied in detail." (PMID 39240063, 2024).
respiratory failure (1 paper, 2025). The significant impairment of gas exchange within the lungs resulting in hypoxia, hypercarbia, or both, to the extent that organ tissue perfusion is severely compromised. "MASLD was present in 50% of patients and independently associated with early respiratory failure (OR 3.8) and vasopressor-dependent shock (OR 4.0), despite similar sCAP severity at baseline." (PMID 40869413, 2025).
SARS-CoV infection (1 paper, 2023). "Thus, should Nsp3 increase the stability of SREBP-2 or of its CTD during SARS-CoV infection, it might also diminish the pool of SCAP available for this step in innate immune response activation." (PMID 37838170, 2023).
thrombosis (1 paper, 2008). "Our results also suggest that this association may be due to the presence of more complicated lesions and thrombosis among the subjects with the SREBF-2 C allele in combination with the SCAP G allele." (PMID 19116028, 2008).
type 1 diabetes (1 paper, 2013). "Western blotting of extracts of brains from streptozotocin (STZ)-treated mice (a model of type 1 diabetes) revealed an ∼50% decrease in SCAP protein in the mouse cerebral cortex." (PMID 23585733, 2013).
vascular dementia (1 paper, 2025). A degenerative vascular disorder affecting the brain. "The vascular-cholesterol cluster includes NBEAL1 (Tier 1) and SCAP (Tier 3), connecting iAging5 to AD and vascular dementia through cholesterol dysregulation." (PMID 41358312, 2025).
vitamin D deficiency (1 paper, 2023). A nutritional condition produced by a deficiency of VITAMIN D in the diet, insufficient production of vitamin D in the skin, inadequate absorption of vitamin D from the diet, or abnormal conversion of vitamin D to its bioactive metabolites. "Recently, vitamin D deficiency was shown to regulate lipid metabolism by inhibiting significant regulators of lipogenesis, including sterol regulatory element-binding protein (SREBP) and SREBP cleavage-activating protein (SCAP)." (PMID 37644450, 2023).
tumor (38 papers, 2010 to 2026). "To investigate what underlies the requirement for SCAP in the PDAC mouse tumor models, we examined the requirement of SCAP for human PDAC cell growth in vitro." (PMID 39240063, 2024). "We have shown that the survival of PDT-treated tumor cells depends on the repair mechanism of cellular membranes mediated by the SCAP/SREBP signaling pathway responsible for the control of cholesterol and fatty acid metabolism." (PMID 39675508, 2025). "Tumor cells bypass this regulation through mechanisms such as EGFR-induced the SREBP cleavage-activating protein (SCAP) glycosylation, enabling SREBP2 activation and increased lipogenesis." (PMID 40370434, 2025). "SCAP/SREBP signaling promotes PD-1 expression in Treg cells, and specific deletion of SCAP of Treg cells leads to an inhibition of tumor growth and an increased effectiveness of anti-PD-1 immunotherapy in mice." (PMID 40097417, 2025). "Unlike fatostatin, which directly binds to SCAP to inhibit the translocation of SREBP2 to the Golgi, the tumor-suppressive effects of betulin primarily rely on enhancing the interaction between SCAP and INSIG." (PMID 40308757, 2025). "Together, these xenograft models demonstrate that SCAP is required for human PDAC tumor growth both subcutaneously and in the pancreas." (PMID 39240063, 2024). "Compared with wild-type human Pa03c cells, SCAP KO Pa03c cells showed significantly decreased tumor growth in subcutaneous xenografts in nude mice." (PMID 39240063, 2024). "Future studies testing the requirement for SCAP in existing tumors will reveal mechanistic details of how SREBP pathway activation supports PDAC tumor growth." (PMID 39240063, 2024). "A more direct and increasingly interesting approach through pharmacological or genetic inhibition of SCAP can significantly inhibit tumor growth in various cancer models." (PMID 36969840, 2023). "As a downstream target of the PI3K-AKT signaling pathway, PCK1 can influence the SCAP/SREBP complex to regulate tumor lipid metabolism." (PMID 37062825, 2023). "The loss of SCAP in tumor Tregs has been shown to increase the proportion of CD8+ T cells and Foxp3-CD4+ T cells in the TME, to inhibit tumor growth and to enhance anti-PD-1 immunotherapy." (PMID 36038892, 2022). "In an elegant set of experiments, the authors demonstrated that accelerated HCC tumor formation was due to the role of SCAP in SREBP activation." (PMID 35642642, 2022). "The results indicated that the levels of expression of both SREBP-1 and SCAP in the NSCLC samples were higher than those in the non-tumor samples, and that these elevated levels were stage-dependent." (PMID 35806291, 2022). "Tumor growth was also decreased in mice with SCAP deleted Treg cells and these mice were also more sensitive to anti-PD1 therapy." (PMID 36077824, 2022). "The abnormalities in the SCAP/SREBP pathway that is involved in lipogenesis are often associated with tumorigenesis and tumor development." (PMID 35631531, 2022). "Glycosylation stabilizes SCAP and reduces its association with Insig-1, allowing movement of SCAP/SREBP to the Golgi and consequent proteolytic activation of SREBP, leading to increasing fatty acid synthesis and tumor growth." (PMID 36038892, 2022). "A further analysis revealed that Tregs needed SREBP/SCAP activity in order to perform their active functions in the tumor site." (PMID 36077824, 2022). "IHC results showed that SCAP-positive tumour cells tended to have higher PCNA expression in the nucleus and showed the lowest proliferation in the Ly + Sora and Sora groups." (PMID 35354475, 2022). "In contrast, mRNA levels of PPARγ and SCAP, which participate in the control of lipid synthesis in intestinal crypts, were both reduced in tumor cells." (PMID 34206240, 2021).
tumor (continued). "Both TGFβ1 and GDF15 belongs to TGF-β superfamily, TGFβ1 was reported to activate SREBP2 in kidney mesangial cells, SREBF2 activation was dependent on SCAP, SCAP or SREBPs promoted tumor progression in various cancer." (PMID 33123476, 2020). "The present results demonstrated the role of SCAP-dependent SREBP suppression in RA-XII-induced anti-tumor and anti-lipogenesis effects." (PMID 31083642, 2019). "Previous studies have established the protein SCAP as an upstream regulator of SREBP-1 involved in tumor lipid metabolism." (PMID 31083642, 2019). "It has been shown that inhibition of SCAP significantly reduces the lipogenesis and tumor cells growth." (PMID 31083642, 2019). "Inhibiting lipid biosynthesis by silencing SREBP1, SREBP2 or their regulator SCAP reduced the rate of cell proliferation as well as tumor-initiating potential in vitro." (PMID 29449559, 2018). "Inhibition of SCAP or SREBPs, either pharmacologically or genetically, has been found to significantly suppress tumor growth in various cancer models, suggesting that SCAP/SREBPs could be promising metabolic targets for cancer prevention and therapy." (PMID 40427160, 2025). "To extend our results from the KPC mice, we tested whether SCAP is required for human PDAC tumor establishment and progression in mouse xenograft models." (PMID 39240063, 2024). "To test whether the growth of human PDAC xenografts requires SCAP in a model that more accurately represents the tumor microenvironment, we utilized an orthotopic xenograft model." (PMID 39240063, 2024). "Collectively, these results demonstrate that both SREBF1 and SREBF2 support PDAC cell and tumor growth, suggesting that SCAP may be a better therapeutic target than either SREBP1 or SREBP2 alone." (PMID 39240063, 2024). "It was found that down-regulation of SREBP expression by targeted SREBP cleavage activating protein (SCAP) increased apoptosis in Treg cells and could be used in combination with PD-1 blockers to activate an anti-tumour immune response." (PMID 38245525, 2024). "Next, we tested whether the requirement of SCAP for PDAC cell and tumor growth was due to loss of SREBP1, SREBP2, or both." (PMID 39240063, 2024). "Using xenograft models, we showed that SCAP is required for human PDAC tumor growth." (PMID 39240063, 2024). "EGFR signaling in cancer cells could promote N-glycosylation of SCAP by increasing glucose uptake and enhance tumor progression." (PMID 37938654, 2023). "On the basis of our previous study, we also believe that SCAP may be involved in the regulation of sorafenib resistance through other mechanisms, such as through the regulation of tumour angiogenesis (VEGFR)." (PMID 35354475, 2022). "Thus, this study revealed the essential role of ammonia in the regulation of SCAP/Insig dissociation, SREBP activation and lipid metabolism, and identified SCAP as a critical sensor connecting glutamine, glucose, and lipid metabolism to promote tumor growth." (PMID 36009491, 2022). "Importantly, liver damage and HCC tumor incidence were less severe in SCAP/ATG5ΔL mice compared with PTEN/SCAPΔL mice, suggesting that other PTEN-dependent functions contribute to the full disease presentation in PTEN/SCAPΔL mice." (PMID 35642642, 2022). "Deletion of SCAP in intratumoral regulatory T cells (Treg cells) inhibited tumour growth." (PMID 35354475, 2022). "Interestingly, SCAP protein expression was significantly higher in HCC tumours and sorafenib-acquired resistant HCC cells." (PMID 35354475, 2022). "Enzymes and transcriptional factors of lipid metabolism including SREBPs, SCAP, FASN and FABP5 are potential targets in Treg cells whose inhibition might be associated with a more restricted anti-tumor response." (PMID 36038892, 2022). "Similarly, our confirmation through western blotting also observed that SREBP-1 and SCAP were highly expressed in tumor site than non-tumor adjacent site of NSCLC samples." (PMID 35806291, 2022).